PLN (phospholamban)
Diseases named in the same sentence as PLN in open-access papers (continued):
Sharing a sentence is not in itself a finding about the gene and the disease.
Obesity (12 papers, 2015 to 2025). Accumulation of substantial excess body fat. "Specifically, obesity was associated with an increased proportion of inhibitory PLN monomers and decreased phosphorylation of PLN, which would typically reduce SERCA2a activity." (PMID 40565066, 2025). "There is still a long way to go before we can fully decipher and understand the precise remodeling of the PLN/SERCA2a domain in HFpEF caused by obesity and T2D." (PMID 35621874, 2022). "Decrease in phosphorylated PLN coupled with an increase in total PLN has been found in animal models of obesity, potentially increasing risk of AF." (PMID 30896405, 2019). "In conclusion, this study demonstrates that obesity causes a paradoxical dysregulation of SERCA2a in atrial myocytes, with increased activity despite higher levels of inhibitory PLN monomers and reduced PLN phosphorylation." (PMID 40565066, 2025). "We propose that obesity enables SERCA2a activation independently of PLN regulation, while adrenergic stimulation triggers arrhythmogenic Ca2+-induced Ca2+ release, promoting AF." (PMID 40565066, 2025). "Our findings indicate that diet-induced obesity increases the proportion of inhibitory PLN monomers and impairs PLN phosphorylation in atrial myocytes." (PMID 40565066, 2025). "The increased abundance of the PLN monomer and impaired PLN phosphorylation suggests that SERCA2a-mediated Ca2+ uptake into the sarcoplasmic reticulum is reduced in our diet-induced obesity model." (PMID 40565066, 2025). "Based on these findings, we propose a novel mechanism where obesity primes SERCA2a for activation independently from PLN regulation, altering Ca2+ signaling in atrial myocytes and leading to atrial fibrillation during sympathetic activation." (PMID 40565066, 2025). "The defective PLN phosphorylation found in our model agrees with previous studies that have shown obesity in rats promotes the reduction of PLN phosphorylation." (PMID 40565066, 2025). "Unexpectedly, obesity increases the proportion of inhibitory PLN monomers and decreases PLN phosphorylation, suggesting decreased SERCA2a activity." (PMID 40565066, 2025). "For obesity/T2D-induced HFpEF, the PLN/SERCA2a microdomain should be of particular functional relevance since it regulates diastolic calcium reuptake and cell relaxation." (PMID 35621874, 2022). "Therefore, we expect that the increased abundance of the PLN monomer and impaired PLN phosphorylation induced by obesity impair intracellular Ca2+ transport in atrial myocytes." (PMID 40565066, 2025). "Hyperlipidemia and obesity have been shown to deteriorate Ca2+ homeostasis through altered expression and phosphorylation of a key protein of the Ca2+ cycling, SERCA2a, and its main regulator phospholamban (PLN)." (PMID 41334452, 2025). "However, obesity increases the proportion of inhibitory phospholamban (PLN) monomers and decreases PLN phosphorylation, suggesting reduced SERCA2a activity." (PMID 40565066, 2025). "However, in this review, we specifically focus on cAMP dynamics within the PLN/SERCA2a microdomain in the etiology of HFpEF induced by obesity and T2D." (PMID 35621874, 2022). "Below, we discuss the importance of the PLN/SERCA2a microdomain and evidence obtained from basic biochemical approaches that suggest the presence of PLN/SERCA2a dysregulation and remodeling of cAMP dynamics in obesity and T2D HFpEF models." (PMID 35621874, 2022). "Collectively, these findings suggest that obesity induces paradoxical dysregulation of SERCA2a in atrial myocytes, stimulating SERCA2a activation despite an increase in the relative abundance of the inhibitory PLN monomer and a reduction in PLN phosphorylation." (PMID 40565066, 2025). "In our animal model of moderate obesity, HFD altered the expression of SERCA2a and affected its regulators PLN and Sln that could potentially impact cardiac function in a complex way." (PMID 41334452, 2025).
Myocardial fibrosis (10 papers, 2014 to 2025). "Transgenic mice expressing the PLN p.Arg14del variant also showed accumulation of myocardial fibrosis and contractile dysfunction by reduced LVEF and increased EDV and ESV." (PMID 35097021, 2021). "Although the direct effects on Ca2+ cycling are part of ongoing discussion, the PLN R14del pathogenic variant is reported to result in PLN protein aggregates, myocardial fibrosis and cardiac dysfunction." (PMID 34462437, 2021). "In the 8 heart slices of PLN mutation carriers, myocardial fibrosis was mainly observed in the trabecular part of the posterolateral wall of the right ventricle and in the posterolateral (mean >38%) and in lesser extent anterolateral (mean >26%) wall of the left ventricle." (PMID 24732829, 2014). "PLN-R14 mice showed cardiac dysfunctions, extensive myocardial fibrosis and the aggregation of PLN proteins in cardiomyocytes, more severe in the homozygous mouse." (PMID 37408239, 2023). "Masson’s trichrome staining revealed a significant prevention of myocardial fibrosis in PLN-ASO treated mice (fold change compared to WT 2.4 ± 0.4 vs. 17.17 ± 4.1%, P value = 0.0032)." (PMID 34462437, 2021). "Furthermore, there was a significant (p < 0.01) increase of myocardial fibrosis in cardiac sections of PLN-R14Δ/+ mice." (PMID 32555305, 2020). "However, low R-wave amplitude or QRS voltages are seen in both ischemic and genetic cardiomyopathy, with genetic mutations in the phospholamban protein being known to cause lowering of QRS voltages over time, which is thought to predispose myocardial fibrosis and dilation of the heart." (PMID 35501785, 2022). "Early PLN-ASO administration strongly reduced formation of myocardial fibrosis in PLN-R14 Δ/Δ mice (~4-fold at 22 weeks), whereas late PLN-ASO administration resulted in collagen deposition at 22 weeks comparable to 8-week-old vehicle-treated PLN-R14 Δ/Δ mice." (PMID 35269571, 2022).
arrhythmogenic right ventricular cardiomyopathy (8 papers, 2015 to 2025). "For example, in patients who experience post-operative AF, SERCA2 is significantly decreased in the atrial tissue, but those with PLN mutations have decreased AF susceptibility in the context of arrhythmogenic right ventricular cardiomyopathy." (PMID 30896405, 2019). "Mutations in PLN can be identified in 2% of DCM patients, and variants in this gene have been particularly associated with arrhythmogenic cardiomyopathies, including right ventricular dysplasia with predominant LV involvement." (PMID 31179125, 2019). "Our aim was to screen 315 patients with arrhythmogenic right ventricular cardiomyopathy (n = 111), DCM (n = 95), hypertrophic cardiomyopathy (n = 40) and peripartum cardiomyopathy (n = 69) for disease-causing PLN mutations by high resolution melt analysis and DNA sequencing." (PMID 26917049, 2016). "Mutations in PLN have been found in dilated cardiomyopathy (DCM), arrhythmogenic right ventricular cardiomyopathy (ARVC) and hypertrophic cardiomyopathy (HCM) patients." (PMID 25928149, 2015).
hypertrophic cardiomyopathy (7 papers, 2016 to 2024). A condition in which the myocardium is hypertrophied without an obvious cause. "In conclusion, WES led to the detection of two heterozygous variants in the ACTC1 gene and in the PLN gene, which represent the probable cause of hypertrophic cardiomyopathy in the patient." (PMID 39273332, 2024). "Pathogenic heterozygous variants in the ACTC1 gene and the PLN gene have been reported to cause hypertrophic cardiomyopathy 11 [OMIM: 612098] and 18 [OMIM: 613874], respectively." (PMID 39273332, 2024). "Next, our KEGG analysis showed that transcripts up-regulated in the mutant cardiomyocytes were related to hypertrophic cardiomyopathy (ACTC1, MYL2, MYL3), Ca2+-dynamics regulatory pathway (ATP2B4, CACNA1C, CAMK2B, PLN), as well as cardiac-muscle contraction transcripts (ACTC1, MYH7, TNNI3, TNNT2)." (PMID 35784482, 2022).
diabetes (6 papers, 2012 to 2020). "On the other hand, it has been reported that diabetes reduces phospholamban phosphorylation, in agreement with our observations." (PMID 28698769, 2017). "In ventricular dysfunction induced by diabetes, multiple mechanisms, including down-regulation of SERCA2a, reduced phosphorylation of phospholamban and leakage of Ca2+ from SR, and increased collagen deposition in the extracellular matrix, have been proposed." (PMID 22768157, 2012). "Alterations in PKA mediated phosphorylation of phospholamban (PLN), ryanodine receptor (RyR) and troponin I (TnI) proteins due to diabetes have been investigated in the studies which we used to generate this review." (PMID 33256212, 2020). "PLN (ranked 7th) was not related to Diabetes in the corresponding OMIM entry, however reports a role of PLN in diabetic cardiomyopathy." (PMID 24564336, 2014). "This fact is also tested in this study: Diabetes induced a markedly increased phosphorylation level of PLN with unchanged levels of both PLN and SERCA, which are in line partially but not fully with previously published data." (PMID 23923043, 2013).
Hyperglycemia (6 papers, 2014 to 2025). An increased concentration of glucose in the blood. "While this study unfortunately did not assess diastolic dysfunction, it highlights the importance of maintaining normal PKA mediated PLN phosphorylation in regulating SERCA2a mediated calcium reuptake in hyperglycemia." (PMID 35621874, 2022). "Ferulic acid is found to be able to prevent mitochondrial dysfunction induced by the hyperglycemia condition in H9c2 cells via the sarcoplasmic reticulum Ca2+-ATPase (SERCA)/phospholamban (PLN) pathway." (PMID 32842567, 2020). "CaMKII senses intracellular calcium (Ca2+) changes, oxidation status, and hyperglycemia to phosphorylate substrates that regulate Ca2+-sensitive proteins, such as L-type Ca2+ channels, phospholamban, and cardiac ryanodine receptors (RyR2)." (PMID 24672485, 2014). "Moreover, PKA inhibitors, but not an Epac blocker, markedly improved hyperglycemia-induced hypertrophy and attenuated the increased SERCA2a expression by LCA; it also attenuated the phosphorylated PLN and SERCA2a protein expression levels in high glucose-treated H9C2 cells." (PMID 30842472, 2019).
myocardial infarction (6 papers, 2014 to 2025). Gross necrosis of the myocardium, as a result of interruption of the blood supply to the area, as in coronary thrombosis. "Finally, in rats with myocardial infarction, PLN-ASO treatment prevents progression of left ventricular dilatation and improves left ventricular contractility." (PMID 34462437, 2021). "The findings demonstrate that AEOL reduces mitochondrial ROS production, decreases myocardial infarct size, and improves cardiac function through NRF2-mediated upregulation of DWORF, which enhances SERCA2a activity by disrupting the phospholamban-SERCA2a interaction." (PMID 40375185, 2025).
hypothyroidism (5 papers, 2022 to 2025). Abnormally low levels of thyroid hormone. "Hypothyroidism impairs myocardial relaxation owing to decreased reuptake of Ca ions via the sarcoplasmic reticulum Ca-ATPase-phospholamban system." (PMID 40242698, 2025). "However, a drop in T3/T4 is most likely not responsible for the decrease in phospholamban and the small increase in SERCA pump expression, since hypothyroidism is well known to increase phospholamban and decrease SERCA." (PMID 36816513, 2023). "This may be explained by an insufficient expression of proteins involved in muscle contraction, since in rats the expression of phospholamban is regulated by thyroid hormones; furthermore, in humans with hypothyroidism, thyroid hormone receptors at the level of the myocardium are underregulated." (PMID 40013294, 2024).
centronuclear myopathy (4 papers, 2015 to 2017). Centronuclear myopathy (CNM) is an inherited neuromuscular disorder characterized by clinical features of a congenital myopathy and centrally placed nuclei on muscle biopsy. "We have recently discovered that type I fiber specific PLN overexpression in mice (PlnOE) causes severe impairments in SERCA function and a centronuclear myopathy (CNM)-like phenotype in the soleus and gluteus minimus muscles." (PMID 28278204, 2017). "A recent study shows that complete loss of SLN fails to improve SERCA function and a centronuclear myopathy-like phenotype in transgenic mice with skeletal muscle specific PLN overexpression." (PMID 29051551, 2017). "Previous work from our laboratory revealed that in the soleus and gluteus minimus muscles of mice overexpressing PLN (PlnOE), SERCA function was impaired, dynamin 2 (3–5 fold) and SLN (7–9 fold) were upregulated, and features of human centronuclear myopathy (CNM) were observed." (PMID 27134770, 2016).
dilatation (4 papers, 2020 to 2025). "LV end-systolic and end-diastolic internal diameters were significantly increased in vehicle-treated R14Δ/Δ mice as compared to WT mice, indicating ventricular dilatation, which was dose-dependently rescued by PLN-ASO administration." (PMID 40905134, 2025). "Both early and late PLN-ASO treatment resulted in less pronounced LV dilatation, and preserved FS and GLS." (PMID 35269571, 2022). "LV end-diastolic and end-systolic volumes were increased, and stroke volume and ejection faction were decreased in PLN-R14Δ/Δ mice as compared to WT controls, indicating ventricular dilatation and contractile dysfunction." (PMID 32555305, 2020). "In contrast to the DCM phenotype that is often found in human patients, PLN-R14Δ/+ mice exhibited no ventricular dilatation." (PMID 32555305, 2020).
familial dilated cardiomyopathy (4 papers, 2018 to 2022). A a genetic form of heart disease that occurs when heart (cardiac) muscle becomes thin and weakened in at least one chamber of the heart, causing the open area of the chamber to become enlarged (dilated). "In the Netherlands, pathogenic variants in the plakophilin‐2 (PKP2) and phospholamban (PLN) gene are the most prevalent genetic predispositions for familial dilated cardiomyopathy (DCM) and arrhythmogenic cardiomyopathy (ACM)." (PMID 33528799, 2021). "Since 2003, several kinds of PLN mutations have been identified in familial dilated cardiomyopathy (DCM) patients, illustrating a few clinical characteristics that differs from classical DCM patients." (PMID 33020536, 2020). "The last group of patients in our present study was the group of familial dilated cardiomyopathy patients (PLN/LMNA group) who had a genetic disorder affecting the genes LMNA and PLN." (PMID 29305677, 2018).
Hypertension (4 papers, 2019 to 2024). The presence of chronic increased pressure in the systemic arterial system. "SERCA2A expression was lowered by both comorbidities, whereas PLN appeared to be principally affected by DS‐induced hypertension." (PMID 31368189, 2019). "As NPPA has been demonstrated to inhibit NFAT activation, this DS‐induced up‐regulation of NPPA could explain why RCAN1 was not up‐regulated in DS‐treated rats, even though crucial Ca2+‐handling genes (ATP1A2, SERCA2A and PLN) were dysregulated upon DS‐induced hypertension." (PMID 31368189, 2019).
Sepsis (4 papers, 2009 to 2024). Sepsis is defined as life-threatening organ dysfunction caused by a dysregulated host response to infection. "Indeed, sepsis induced decrease of phospholamban phosphorylation level was alleviated by DPP4 deficiency, and associated with the cardiac function preservation." (PMID 24416433, 2014). "Phospholamban (Pln), cadherin-2 (Cdh2) and Nprl3 are found to participate in the pathogenesis of sepsis and promote inflammation." (PMID 38601461, 2024). "Western blot analysis indicated that the expression of phosphorylated PLN in Serine 16 instead of Threonine 17 decreased in TLR7−/− mice in response to sepsis compared with WT mice, along with downregulation of phosphorylated PKA." (PMID 33463061, 2021). "For example, reduced phospholamban phosphorylation by protein kinase inhibition and activation of protein phosphatases that dephosphorylate phospholamban typically observed in sepsis may in turn alter inotropic and relaxation responsiveness with changes in frequency of heart stimulation." (PMID 19196490, 2009). "In addition to reduced phospholamban th-17 phosphorylation and increased phosphatase activity, sepsis could also alter FDAR through multiple mechanisms, such as altered beta-adrenergic signalling and cAMP-dependent kinase activity, myofibrillar dysfunction and disturbed nitric oxide signalling." (PMID 19196490, 2009).
atrial fibrillation (3 papers, 2023 to 2025). A disorder characterized by an electrocardiographic finding of a supraventricular arrhythmia characterized by the replacement of consistent P waves by rapid oscillations or fibrillatory waves that vary in size, shape and timing and are accompanied by an irregular ventricular response. "Defective PLN phosphorylation has also been observed in animal models and patient samples of atrial fibrillation." (PMID 40565066, 2025). "The p.Leu39Ter variant in the PLN gene has also been found in a heterozygous state in a 61-year-old female patient with familial HCM and a clinical history of recurrent atrial fibrillation, palpitations, dyspnea, and presyncope and in large cohort studies of HCM patients." (PMID 39273332, 2024).
familial cardiomyopathies (3 papers, 2010 to 2025). "While the genetic basis of familial cardiomyopathies has been extensively explored, the role of specific pathogenic variants, such as p.Arg14del (R14del, R14∆/+) in the phospholamban (PLN) gene, in disease onset and progression remains an area of active investigation." (PMID 40048085, 2025). "A greater understanding of the role of this domain in regulating PLN in cardiac muscle appears further warranted, given our recent finding that a deletion in the human PLN gene, deleting arginine 14 (RΔ14) results in lethal hereditary cardiomyopathy." (PMID 20634894, 2010). "Furthermore, fibrosis and fatty changes among phospholamban carriers may also occur in a distinct pattern compared to other forms of hereditary cardiomyopathies." (PMID 30806910, 2019).
ischemia (3 papers, 2019 to 2023). A hypoperfusion of the BLOOD through an organ or tissue caused by a PATHOLOGIC CONSTRICTION or obstruction of its BLOOD VESSELS, or an absence of BLOOD CIRCULATION. "Thus, our data establish that antisense inhibition of PLN is an effective strategy in preclinical models of genetic cardiomyopathy as well as ischemia driven HF." (PMID 34462437, 2021). "In acute-on-chronic ischemia, ABCB5+ MSCs treated mice showed a higher microvascular density, increased SERCA2a expression and PLN phosphorylation relative to untreated controls." (PMID 36759868, 2023).
metabolic syndrome (3 papers, 2016 to 2022). A cluster of metabolic risk factors for CARDIOVASCULAR DISEASES and TYPE 2 DIABETES MELLITUS. "Additionally, in response to a high-carbohydrate-diet-induced metabolic syndrome in rats, elevated PDE3 and PDE4 expression was associated with a decreased phosphorylation of PLN and altered calcium homeostasis." (PMID 35621874, 2022).
ventricular tachycardia (3 papers, 2021 to 2023). A disorder characterized by an electrocardiographic finding of three or more consecutive complexes of ventricular origin with a rate greater than a certain threshold (100 or 120 beats per minute are commonly used). "The delayed ventricular activation and conduction times predispose the R14Rdel-PLN mice to reentrant ventricular tachycardia (VT)." (PMID 34204946, 2021). "Importantly, disruption of the human R14del-PLN allele with AAV9-CRISPR/Cas9 improved cardiac function and reduced ventricular tachycardia susceptibility in the humanized R14del-PLN mice." (PMID 36768995, 2023).
chronic heart failure (2 papers, 2019 to 2025). "In contrast, PLN R9C is a missense mutation identified in patients with DCM with refractory congestive heart failure, and transgenic mice carrying Pln R9C recapitulate human DCM with sudden cardiac death." (PMID 39772618, 2025).